ATP8A2 (ATPase phospholipid transporting 8A2)
Diseases named in the same sentence as ATP8A2 in open-access papers:
ATP8A2 is named in the same sentence as 52 diseases in open-access papers, as found by Europe PMC text mining. Sharing a sentence is not in itself a finding about the gene and the disease. The quoted sentences say what the papers report.
cerebellar ataxia (14 papers, 2014 to 2024). A neurological syndrome characterized by clumsy and uncoordinated movement of the limbs, trunk, and cranial muscles. "We determined the expression, localization and ATPase activity of four variants of ATP8A2, the P4-ATPase associated with the neurodevelopmental disorder known as cerebellar ataxia, impaired intellectual development and disequilibrium syndrome 4 (CAMRQ4)." (PMID 38436085, 2024). "ATP8A2 translocates phosphatidylserine (PS) in the central nervous system, and a mutation in the ATP8A2 gene causes cerebellar ataxia mental retardation and disequilibrium syndrome in humans." (PMID 38280458, 2024). "Pathogenic variants in ATP8A2 are known to cause cerebellar ataxia, impaired intellectual development, and disequilibrium syndrome 4 (CAMRQ4) which is often associated with encephalopathy, global developmental delay, and severe motor deficits." (PMID 39066872, 2024). "Mutations in the gene encoding ATP8A2 have been linked to the neurodevelopmental disorder known as cerebellar ataxia, impaired intellectual development and disequilibrium syndrome 4 (CAMRQ4)." (PMID 38436085, 2024). "Biallelic mutations in ATPase, class 1, type 8 A, member 2 (ATP8A2) (MIM:605870) cause cerebellar ataxia, impaired intellectual development, and disequilibrium syndrome 4 (CAMRQ4, MIM:615268)." (PMID 39066872, 2024). "Deletion of TMEM30A from mouse cerebellar Purkinje cells was shown to cause early onset cerebellar ataxia, while ATP8A2 mutations are associated with CAMRQ syndrome characterized by cerebellar ataxia and quadrupedal locomotion." (PMID 35420383, 2022). "Two ATP8A2-deficient mouse models, wabbler-lethal (wl) mouse and ATP8A2 knockout mouse, show similar neurological abnormalities including body tremors and ataxia resulting from distal axonal degeneration of the spinal cord." (PMID 27458383, 2016). "Mice carrying loss-of-function mutations in the Atp8a2 gene develop axonal degeneration resulting in progressive ataxia and neurodegeneration." (PMID 24904274, 2014). "We note that murine P4-ATPases ATP8A1 and ATP8A2 are expressed in the nervous system, and knockout mice exhibit deficient hippocampal learning, sensory deficits, cerebellar ataxia, mental retardation, and spinal cord degeneration, and shortened photoreceptor NRE length." (PMID 33759761, 2021). "ATP8A2, another P4-ATPase highly expressed in the brain, has been implicated in a recessive disorder characterized by cerebellar ataxia, ID, and disequilibrium syndrome (CAMRQ, MIM 615268), or severe hypotonia, ID, and optic atrophy with or without encephalopathy." (PMID 34764295, 2021). "A missense mutation located in a M domain of ATP8A2 is associated with cerebellar ataxia, mental retardation and dysequilibrium syndrome (CAMRQ), an autosomal recessive disorder characterized by dysarthric speech and cerebellar atrophy with or without quadrupedal gait." (PMID 24904274, 2014). "Mutations in Atp8a2 cause axonal dystrophy, axonal degeneration in the medial cerebellar nuclei, and retinal degeneration in mice, and a severe neurological disorder in humans that is characterized by cerebellar ataxia, mental retardation, and disequilibrium syndrome." (PMID 30185775, 2018). "The naturally occurring Atp8a2 mutant mice, wabbler-lethal mice, showed progressive ataxia with pronounced neurodegeneration in the central and peripheral nervous system and die in the early life period." (PMID 31071093, 2019). "Loss of Atp8a2 in DCN led to degenerated neurons, which caused ataxia-like phenotypes, similar to that of Tmem30a KO." (PMID 30185775, 2018). "Thus, although both ATP8A2 and TMEM30A deficiencies cause cerebellar ataxia, the underlying cellular mechanisms differ." (PMID 35420383, 2022). "Disruption of Atp8a2 in DCN led to degenerated neurons, causing ataxia-like phenotypes)." (PMID 30185775, 2018).
cerebellar ataxia (continued). "In addition, disruption of ATP8A2 leads to severe neurological disorders that are characterized by cerebellar ataxia, mental retardation and disequilibrium syndrome in humans." (PMID 28839191, 2017). "In humans, a loss-in-function mutation in ATP8A2 is responsible for CAMRQ syndrome, a severe disease characterized by cerebellar ataxia, mental retardation, and dysarthric speech with or without quadrupedal gait." (PMID 30018401, 2018).
breast carcinoma (6 papers, 2015 to 2025). "A risk model incorporating ATP8A2 has been developed to predict the survival of patients with luminal A breast cancer." (PMID 40672387, 2025). "Also, ATP8A2-Ψ was shown to induce tumor progression when overexpressed in breast cancer cell lines." (PMID 25765044, 2015). "ATP8A2-Ψ is an especially interesting case, because it is the first published example of a pseudogene that is differentially expressed among cancer subtypes, showing high expression in breast cancer samples with luminal histology but very little expression in basal samples." (PMID 25765044, 2015). "Some genes contribute a lot to the riskscore, however, their roles in breast cancer were largely unstudied, for instance, Peroxidasin like (PXDNL), ATPase phospholipid transporting 8A2 (ATP8A2) and plasminogen activator, tissue type (PLAT)." (PMID 35443644, 2022). "Interestingly, this analysis confirmed that the expression of ATP8A2-pg is virtually absent in the basal-like breast cancer subtype." (PMID 26442270, 2015).
Intellectual disability (5 papers, 2012 to 2025). "And ATP8A2 is reported to be associated with disorders such as intellectual disability, severe hypotonia, choreoathetosis, and optic atrophy." (PMID 40630931, 2025). "Mutations in the ATP8A2 gene have been reported to cause severe recessive neurological diseases in humans, characterized by encephalopathy, intellectual disability, cerebellar atrophy and optic atrophy." (PMID 33525573, 2021). "Mutations in ATP8A2 have also been linked to encephalopathy, intellectual disability, severe hypotonia, chorea and optic nerve atrophy in patient populations." (PMID 30018401, 2018). "Mutations in ATP8A2 have been associated with mental retardation." (PMID 22506031, 2012). "ATP8A2 mutations have been identified as the underlying cause of CAMRQ4 syndrome which is characterized by encephalopathy, intellectual disability, severe hypotonia, psychomotor delay, chorea, and optic atrophy." (PMID 39066872, 2024).
optic atrophy (5 papers, 2018 to 2025). A disorder characterized by loss of optic nerve fibers. "Our observations confirm that biallelic ATP8A2 mutations cause a distinct clinical phenotype that is characterized by global developmental delays, severe hypotonia, optic atrophy and hyperkinetic movement disorders." (PMID 30012219, 2018). "ATP8A2 is also strongly expressed in the retina, and some patients have presented with impaired visual acuity, nystagmus, ophthalmoplegia, and bilateral optic disk atrophy." (PMID 39066872, 2024). "More recently, ATP8A2 has been linked to a phenotype of intellectual disability, severe hypotonia, chorea and optic atrophy without obvious radiographic evidence of cerebellar atrophy." (PMID 30012219, 2018).
CAMRQ syndrome (3 papers, 2016 to 2025). "Our study contributes to the growing body of knowledge on CAMRQ syndrome by expanding on the clinical and genetic aspects of a novel in‐frame deletion variant in the ATP8A2 gene." (PMID 39931767, 2025). "The additional clinical and genetic data presented here further validate the likely pathogenic role of the ATP8A2 variant in CAMRQ syndrome." (PMID 39931767, 2025). "Further research is essential to elucidate the molecular mechanisms underlying CAMRQ syndrome, develop targeted therapeutic strategies, and explore the broader implications of ATP8A2 mutations in diverse populations." (PMID 39931767, 2025). "Our findings expand the mutational spectrum of ATP8A2‐associated CAMRQ syndrome and underscore the importance of comprehensive genetic testing in diagnosing rare neurological disorders." (PMID 39931767, 2025). "The identification of an in‐frame deletion variant in the ATP8A2 gene enhances our understanding of CAMRQ syndrome and highlights the phenotypic variability of the disorder." (PMID 39931767, 2025). "The identification of this variant expands the mutational spectrum of ATP8A2‐associated CAMRQ syndrome and underscores the importance of comprehensive genetic testing in diagnosing rare neurological disorders." (PMID 39931767, 2025). "Genetic analysis revealed a homozygous in‐frame deletion variant (c.1286_1288delAGA) in the ATP8A2 gene, implicating ATP8A2 in the pathogenesis of CAMRQ syndrome." (PMID 39931767, 2025). "However, ATP8A2 is expressed not only in the retina, but all over the brain, where it is indispensable, as evidenced by the CAMRQ syndrome resulting from a single missense mutation of ATP8A2." (PMID 27458383, 2016). "CAMRQ syndrome can arise from pathogenic variants in several genes including the very low‐density lipoprotein receptor (VLDLR) (CAMRQ1; MIM: 224050), WD repeat domain 81 (WDR81) (CAMRQ2; MIM: 610185), carbonic anhydrase 8 (CA8) (CAMRQ3; MIM: 613227) and ATP8A2 designated as CAMRQ4 (MIM: 615268)." (PMID 39931767, 2025).
Cerebellar atrophy (3 papers, 2018 to 2024). Cerebellar atrophy is defined as a cerebellum with initially normal structures, in a posterior fossa with normal size, which displays enlarged fissures (interfolial spaces) in comparison to the foliae secondary to loss of tissue. "Mutations in ATP8A2 lead to severe neurological defects characterized by cerebellar atrophy, mental retardation and disequilibrium syndrome in humans." (PMID 30185775, 2018). "As mutations in ATP8A2 cause cerebellar atrophy, mental retardation, and disequilibrium syndrome in humans, this promoted us to explore the roles of Temem30a in the cerebellum." (PMID 30185775, 2018). "Additionally, individuals with ATP8A2 mutations may exhibit other neurological manifestations such as tremors, seizures, and/or abnormal brain imaging, especially cerebellar atrophy." (PMID 39066872, 2024).
Chorea (3 papers, 2018 to 2024). Chorea (Greek for 'dance') refers to widespread arrhythmic involuntary movements of a forcible, jerky and restless fashion. "All patients with ATP8A2 mutations (100%) demonstrated developmental delay, severe hypotonia and movement disorders, specifically chorea or choreoathetosis (100%), dystonia (27%) and facial dyskinesia (18%)." (PMID 30012219, 2018).
developmental delay (3 papers, 2018 to 2024). "ATP8A2 gene mutations have emerged as the cause of a novel neurological phenotype characterized by global developmental delays, severe hypotonia and hyperkinetic movement disorders, the latter being an important distinguishing feature." (PMID 30012219, 2018).
lung adenocarcinoma (3 papers, 2017 to 2024). A carcinoma that arises from the lung and is characterized by the presence of malignant glandular epithelial cells. "A study of differential gene expression analysis revealed that ATP8A2 and four other genes, each harboring one of the five frequently hypermethylated CpG sites within its promoters, were frequently downregulated in lung adenocarcinoma (LUAD)." (PMID 37686603, 2023). "Additionally, ATP8A2 was found as 1 of 18 prognostic biomarkers in an analysis of the integrated relationship between nuclear mitochondrial genes (NMGs) and the progression of lung adenocarcinoma." (PMID 37686603, 2023). "Accordingly, we found five genes (HOXA9, TAL1, ATP8A2, ENG and SPARCL1) corresponding to the five CpG sites had above 90% hypermethylation frequencies in the 539 lung adenocarcinoma samples from TCGA." (PMID 28178989, 2017). "Gene expression analysis revealed that four of the five genes, HOXA9, TAL1, ATP8A2, ENG and SPARCL1, each harboring one of the five frequently hypermethylated CpG sites within its promoters, were also frequently down-regulated in lung adenocarcinoma." (PMID 28178989, 2017).
Failure to thrive (2 papers, 2018 to 2019). Failure to thrive (FTT) refers to a child whose physical growth is substantially below the norm. "Mouse models of ATP8A2 deficiency have demonstrated that Atp8a2 mutations result in impaired axonal transport, axonal loss, failure to thrive and clinical manifestations of neurodegenerative disease which are similar to the patients we describe." (PMID 30012219, 2018).
lung carcinoma (2 papers, 2021 to 2025). "ATP8A2 has been associated with a better prognosis in lung cancer." (PMID 41264656, 2025). "Though the relationship between ATP8A2 and lung cancer is poorly investigated, a recent study found the alteration in its expression was associated with the prognosis of LUAD." (PMID 34760888, 2021). "Although these genes were previously reported in some cancer types, their specific role in lung cancer is unclarified except for ATP8A2 and RRM2B." (PMID 34760888, 2021).
prostate carcinoma (2 papers, 2020 to 2022). A carcinoma that arises from epithelial cells of the prostate gland. "There are a multitude of other regulatory pseudogene-gene relationships that have been validated including FTH1-FTH1PX (X denotes multiple pseudogenes) in prostate cancer, SUMO1-SUMO1P3 in gastric cancer, ATP8A2-ATP8A2Ψ in breast cancer." (PMID 32241256, 2020).
Cognitive impairment (1 paper, 2018). Abnormal cognition is characterized by deficits in thinking, reasoning, or remembering. "ATP8A2 mutations have recently been described in several patients with severe, early-onset hypotonia and cognitive impairment." (PMID 30012219, 2018).
progressive ataxia (1 paper, 2020). "Last, there were three genes (ITPR1, ATP8A2, and ATXN10) that overlapped with a gene set of hereditary progressive ataxia (n = 59) and the SN-meta-DEGs (p = 0.4320)." (PMID 33390883, 2020).
schizophrenia (1 paper, 2012). A major psychotic disorder characterized by abnormalities in the perception or expression of reality. "Five were not located in any gene, and four were located in genes (ATP8A2, LHFP, PHF11, RCBTB1, and PIBF1 (C13orf24)) not yet shown to be associated with schizophrenia." (PMID 22214315, 2012).
vascular dementia (1 paper, 2025). A degenerative vascular disorder affecting the brain. "Loci CAMK2D and ATPase phospholipid transporting 8A2 (ATP8A2) were also replicated with these two exposures for vascular dementia, whereas loci iodothyronine deiodinase 2 (DIO2) and PSMG1 were replicated with oily fish intake and ω-3 concentrations." (PMID 40949174, 2025).
cancer (5 papers, 2011 to 2022). A tumor composed of atypical neoplastic, often pleomorphic cells that invade other tissues. "Adenosine triphosphatase phospholipid transporting 8A2 (ATP8A2) participates in gene methylation, reduces mRNA expression, and alters expression to disrupt the differentiation state of precancerous cells in various cancers, including BC." (PMID 36072666, 2022). "The pseudogenes SUMO1P3, ATP8A2-Ψ, and Nanog-p8 have each been shown to enable cancer progression, but the mechanisms by which they do this are unknown." (PMID 25765044, 2015). "We found that SPARCL1, ENG, TAL1, ATP8A2 and HOXA9 were down-regulated in 99, 94, 89, 65 and 49% of the 82 cancer samples." (PMID 28178989, 2017). "Two of the genes (KIF17 and ATP8A2) showed no methylation in either cancer or matched tissues, and eight genes (EPHA4, OVOL1, UTF1, ADAM8, BOLL, FOXE3, GUCY1A2, and ADCY5) were equally methylated in the two groups." (PMID 21625442, 2011).
neurological disorders (5 papers, 2012 to 2025). "ATp8A2 is a known coding gene associated with complex neurological diseases and has high mRNA expression in hippocampal neurons." (PMID 33525573, 2021). "As this gene involves neurite elongation and neuron survival, various genomic variants of ATP8A2 are identified in patients with neurological disorders." (PMID 34760888, 2021). "Clinical and genetic analyses confirm its pathogenicity, expanding the mutational spectrum of ATP8A2‐related CAMRQ and underscoring the importance of comprehensive genetic testing in rare neurological disorders." (PMID 39931767, 2025). "However, this patient together with the data presented in our current paper suggests that ATP8A2 should be further considered as a candidate gene for human neurological diseases." (PMID 22912588, 2012).
neurodevelopmental disorder (4 papers, 2017 to 2026). A behavioral and cognitive disorder with onset during the developmental period that involves impaired or aberrant development of intellectual, motor, or social functions. "Recently, two mutations on ATP8A2 were reported to be associated with various neurodevelopmental disorders through protein misfolding." (PMID 40949174, 2025). "This highlights the need for further investigation into the epigenetic and transcriptional complexity of ATP8A2-related neurodevelopmental disorders." (PMID 42029640, 2026).
tumor (2 papers, 2015 to 2021). "ATP8A2 was hypermethylated in tumor tissues and, therefore, poorly expressed in the tumor tissues compared with the normal tissues." (PMID 34760888, 2021). "For example, the second pseudogene on the list is ATP8A2-Ψ, a pseudogene that has been found to be upregulated in luminal subtypes and shown to induce tumor progression." (PMID 25765044, 2015).
ATP8A2 also shares sentences with these, for which no sentence is quoted: Ataxia (4 papers); Encephalopathy (3); Buruli ulcer (2); Choreoathetosis (2); infection (2); acute myelogenous leukemia (1); cerebral infarction (1); diabetes (1); Dystonia (1); eczema (1); experimental autoimmune encephalomyelitis (1); fish eye disease (1); genetic diseases (1); glioblastoma (1); glioma (1); Glycogen storage disease type Ib (1); hyperlipidemia (1); inflammatory bowel disease (1); inflammatory brain diseases (1); ischemia (1); leukodystrophy (1); mevalonic aciduria (1); microcephaly (1); movement disorder (1); neurodegenerative disease (1); neutropenia (1); oculocerebrorenal syndrome of Lowe (1); Parkinson disease (1); progressive familial intrahepatic cholestasis type 1 (1); sarcoidosis (1).
A further 2 diseases each share a sentence with ATP8A2 in 1 paper.